CNGB1 (cyclic nucleotide gated channel subunit beta 1)
Description:
Pore-forming subunit of the rod cyclic nucleotide-gated channel. Mediates rod photoresponses at dim light converting transient changes in intracellular cGMP levels into electrical signals. In the dark, cGMP levels are high and keep the channel open enabling a steady inward current carried by Na(+) and Ca(2+) ions that leads to membrane depolarization and neurotransmitter release from synaptic terminals. Upon photon absorption cGMP levels decline leading to channel closure and membrane hyperpolarization that ultimately slows neurotransmitter release and signals the presence of light, the end point of the phototransduction cascade (By similarity). Pore-forming subunit of the olfactory cyclic nucleotide-gated channel. Operates in the cilia of olfactory sensory neurons where chemical stimulation of the odorant is converted to an electrical signal. Mediates odorant-induced cAMP-dependent Ca(2+) influx triggering neuron depolarization. The rise of intracellular Ca(2+) levels potentiates the olfactory response by activating Ca(2+)-dependent Cl(-) channels, but it also serves as a negative feedback signal to desensitize the channel for rapid adaptation to odorants (By similarity). Conducts cGMP- and cAMP-gated ion currents, with permeability for monovalent and divalent cations. The selectivity for Ca(2+) over Na(+) increases with cGMP concentrations, whereas the selectivity among monovalent ions is independent of the cGMP levels (By similarity). [Isoform GARP2]: High affinity rod photoreceptor phosphodiesterase (PDE6)-binding protein that modulates its catalytic properties: it is a regulator of spontaneous activation of rod PDE6, thereby serving to lower rod photoreceptor 'dark noise' and allowing these sensory cells to operate at the single photon detection limit.
Synonyms: CNG4; GARP; CNCG2; CNCG3L; CNCG4; RCNC2; RCNCb; GAR1; CNGB1B; RP45; GARP2; RCNCbeta
Tractability: Small molecule: a structure with a bound ligand is known; it belongs to a druggable protein family. Antibody: its Gene Ontology location is reachable by antibodies, with high confidence; UniProt places it where antibodies can reach, with medium confidence; UniProt predicts a signal peptide or a membrane-spanning region; the Human Protein Atlas places it where antibodies can reach.
Gene: Protein-coding gene on chromosome 16 (57,882,340 to 57,971,128, reverse strand). Ensembl gene ENSG00000070729.
Subcellular location: Cell membrane; Cell projection, cilium membrane
Subcellular location (Human Protein Atlas): Cytosol; Plasma membrane
Pathways (Reactome):
Sensory Perception: Activation of the phototransduction cascade; Inactivation, recovery and regulation of the phototransduction cascade; Olfactory Signaling Pathway
Organelle biogenesis and maintenance: VxPx cargo-targeting to cilium
Gene Ontology:
Molecular function: cAMP binding; cGMP binding; intracellularly cAMP-activated cation channel activity; intracellularly cGMP-activated cation channel activity; protein binding; ligand-gated monoatomic ion channel activity; cyclic nucleotide-activated monoatomic ion channel activity; intracellularly cyclic nucleotide-activated monoatomic cation channel activity; monoatomic ion channel activity; protein-containing complex binding
Biological process: detection of light stimulus involved in visual perception; monoatomic cation transport; retina homeostasis; visual perception; calcium ion transport; detection of chemical stimulus involved in sensory perception of smell; G protein-coupled receptor signaling pathway; membrane depolarization; monoatomic cation transmembrane transport; olfactory nerve maturation; potassium ion transport; response to odorant; sensory perception of smell; sodium ion transport; monoatomic ion transport; regulation of cytosolic calcium ion concentration; transmembrane transport
Cellular component: transmembrane transporter complex; ciliary membrane; Golgi-associated vesicle membrane; intracellular cyclic nucleotide activated cation channel complex; non-motile cilium membrane; photoreceptor outer segment; photoreceptor outer segment membrane; plasma membrane; rod photoreceptor outer segment; membrane; terminal bouton
Genetic constraint (gnomAD): Loss-of-function variants: 126 observed, 155.43 expected, observed/expected ratio (o/e) 0.81, 90% interval 0.7 to 0.94. The upper end of that interval is the gene's LOEUF score, 0.94, which puts it in group 3 of 6, group 1 being the genes least tolerant of losing a copy. Missense variants: 1,698 observed, 1,667.9 expected, observed/expected ratio (o/e) 1.02, 90% interval 0.98 to 1.06. Synonymous variants: 623 observed, 653.06 expected, observed/expected ratio (o/e) 0.95, 90% interval 0.89 to 1.02.
Gene-disease validity (ClinGen):
ClinGen rates the evidence that CNGB1 causes each of these diseases.
CNGB1-related retinopathy (autosomal recessive): Definitive. An inherited retinopathy caused by bi-allelic variants in the CNGB1 gene.
Homologues: Orthologues: macaque ZNF319 (94% identical), dog CNGB1 (74% identical), rat Cngb1 (74% identical), mouse Cngb1 (74% identical), Drosophila melanogaster CngB (22% identical), Caenorhabditis elegans tax-2 (19% identical), Caenorhabditis elegans tax-4 (14% identical), Drosophila melanogaster CngA (14% identical), Drosophila melanogaster Cngl (13% identical), Caenorhabditis elegans cng-2 (11% identical), Drosophila melanogaster Elk (10% identical), Drosophila melanogaster CG6026 (10% identical), and 3 more. Paralogues in human: CNGB3 (30% identical), CNGA3 (15% identical), CNGA2 (15% identical), CNGA1 (14% identical), HCN4 (13% identical), HCN1 (13% identical), CNGA4 (13% identical), HCN2 (12% identical), HCN3 (12% identical), KCNH4 (12% identical), KCNH3 (11% identical), KCNH8 (11% identical), and 5 more.